TLR3 (toll like receptor 3)
Diseases named in the same sentence as TLR3 in open-access papers (continued):
Sharing a sentence is not in itself a finding about the gene and the disease.
viral infection (continued). "Uncontrolled or sustained innate immune response via TLR3 has been shown to contribute to morbidity and mortality in certain viral infection models, suggesting that the modulation of the TLR3 pathway may offer an attractive strategy to protect against a variety of diseases." (PMID 27504984, 2016). "TLR3 can directly trigger apoptosis in human cancer cells in response to the double-strand RNA synthetic agonist polyinosinic-polycytidylic acid (poly(I:C)), which is a mimic for viral double-stranded RNA that triggers an innate immune response following viral infection." (PMID 27533082, 2016). "However, there is also evidence that TLR3 senses endogenous mRNA from damaged tissue and might maintain inflammation independently of viral infection." (PMID 26536229, 2015). "TLR-3 may play a central role in host responses to viral infections." (PMID 26021751, 2015). "Indeed, we have previously demonstrated that the TLR3-IFN-β pathway is desensitized in MS patient PBMCs, suggesting that MS patients may be pre-sensitized to viral infection showing some form of TLR3 tolerance." (PMID 26283920, 2015). "Thus, through targeting the TLR3 signalling pathway, miR-155 might exert a regulatory activity that limits the over-production of type I interferon and inflammatory cytokines during viral infection and other stimuli." (PMID 25938551, 2015). "Thus, the control of TLR3 immunity is critical in viral infection." (PMID 25938551, 2015). "Besides TLR3, the helicase retinoic acid-inducible gene I (RIG-I) and melanoma differentiation-associated gene 5 (MDA5) may also act as sensors of viral infections by recognition of viral dsRNA." (PMID 25419735, 2014). "Thus, TLR3 plays an important role in the host response to viral infections." (PMID 24709775, 2014). "TLR3 upregulation has been observed in experimental simian immunodeficiency virus (SIV) infection and HIV encephalitis in humans, suggesting that enhanced TLR3 expression during viral infection may predispose cells to a greater response." (PMID 25101306, 2014). "However, patients with MyD-88 and IRAK-4 deficiency show no impaired defense against viral infections, due to their normal functional natural killer cells as well as their retained ability to signal through TLR-3/-7/-9 and other non-TLR viral receptors." (PMID 25528552, 2014). "Activation of the pattern-recognition receptor TLR3 by HCV-RNA and poly (I:C) induces the expression of proinflammatory cytokines, chemokines and adhesion molecules and might thereby directly contribute to viral disease-associated vasculitis." (PMID 25419735, 2014). "Therefore, TLR3 agonists and antagonists might be efficient adjunctive therapies for viral infections depending on the context." (PMID 24302927, 2013). "TLR3 may therefore be primarily important for combating virus infections in the CNS." (PMID 23435233, 2013). "Furthermore, responsiveness of tlr3 gene expression to viral infections, suggests a conserved role of this receptor in the recognition of viral RNA, which is further supported by the fact that poly(I:C) stimulation of HEK293 cells expressing zebrafish tlr3 led to NFκB induction." (PMID 21366518, 2011). "In addition, several studies have indicated that TLR3-mediated signals play either no role or a pathogenic role in viral diseases." (PMID 22189096, 2011). "However, it is likely that endogenously released LL37 may have a physiological role in activating TLR3 during viral infection for the following reasons: LL37 is generated from hCAP-18 by proteolysis." (PMID 22039520, 2011). "TLR3 was also shown to play a minor role in the immune response to mouse cytomegalovirus (MCMV) and murine norovirus as TLR3 deficient mice were observed to harbor increased viral titers following infection although this did not affect their capacity to survive viral infection." (PMID 19122812, 2009).
viral infection (continued). "Thus, TLR3 activation may be one mechanism through which viral infections contribute toward exacerbation of respiratory disease." (PMID 19486528, 2009). "dsRNA is elevated in stress conditions such as viral infection and is recognized by PRRs, including RIG-I, MDA5, PKR, and TLR3, leading to the activation of the innate immune response and the production of antiviral cytokines." (PMID 41395469, 2025). "In polarized intestinal epithelial cells, TLR3 was localized basolaterally, leading to a stronger induction of IFN-λ upon basolateral virus infection." (PMID 40431605, 2025). "ATRA alone upregulated TLR3, TLR4 and RIG-I intestinal epithelial cells, however it suppressed TLR3, TLR7 and RIG-I expression following viral infections." (PMID 40666513, 2025). "Given that the protein level of MyD88 expression remains unaltered following HSV-1 infection, viral infection leads to an elevation in the mRNA levels of TLR2 and TLR3, an effect that can be mitigated by PVE30." (PMID 38185640, 2024). "TLR-3 and TLR-7 closely interact with STAT-3, which is crucial for regulating cytokine-mediated responses, such as IL-6 to combat viral infections." (PMID 39281683, 2024). "Poly(I:C) is a synthetic analogue of a double-stranded viral RNA that binds to toll-like receptor 3 (TLR3), triggering an immune reaction similar to a viral infection." (PMID 39595123, 2024). "Due to their ability to recognize double-stranded RNA (dsRNA), TLR3 and TLR22, which are present on trout skin CD8+ DCs, indicate that these cells are capable of identifying viral infections and then using cross-presentation to activate CD8+ T cells." (PMID 39483482, 2024). "Our findings provide insights into the TLR3-TRIF signaling pathway and MAVS in viral infections, and suggest TLR3-mtROS as a therapeutic target for the treatment of airway inflammatory and viral infectious diseases." (PMID 38203397, 2023). "Toll-like receptor 3 (TLR3) plays an important role in double-stranded RNA recognition and triggers the innate immune response by acting as a key receptor against viral infections." (PMID 38203397, 2023). "The results showed that the mRNA expression of IFN-β, IRF7, MDA5, TLR3, PKR, and MX-1 was significantly decreased in the overexpression group after viral infection, compared with the control group." (PMID 36995259, 2023). "The patient’s cells would therefore probably display normal type I IFN production following the stimulation of TLR3 by dsRNA (including normal baseline IFN-β levels), and during the course of viral infection." (PMID 37083451, 2023). "Polyriboinosinic–polyribocytidilic acid (poly(I:C)), a viral double-stranded RNA mimetic, typically found in some viruses and activates Toll-like receptor 3 (TLR3), was also used experimentally to model viral infections in vivo." (PMID 35453561, 2022). "LncRNA‐155 is regulated by RIG‐I and TLR3, which are critical sensors for type I IFN signalling during viral infection." (PMID 35201667, 2022). "Within the context of viral infections, viral PAMPs, such as viral dsRNA and dsDNA are sensed by PRRs, like RIG-I, MDA5, and TLR3, and PRR activation mediates strong expression of IFNs and ISGs." (PMID 35933402, 2022). "Based on our studies of PARs in ssRNA virus infections, as well by others, we proposed a model in which PAR2 enhances TLR3-NFκB inflammation but reduces TLR3-type-I IFN responses." (PMID 34925374, 2021). "In this current study, we identified three immune response molecules, which were earlier known to have immunity against viral infection such as RIGI, TLR7, and TLR3." (PMID 34970593, 2021). "To emulate OECs behavior under viral infections, we challenged TR146 cells with poly(I:C), a synthetic analog of viral dsRNA that activates TLR3." (PMID 35126344, 2021).
viral infection (continued). "The expression of both TLR3 and TLR7 was found to remain more of less stable at early time points following viral infection." (PMID 33799906, 2021). "To further our analysis, we used Poly(I:C), a synthetic dsRNA compound that binds Toll- like receptor 3 (TLR3), to mimic a viral infection." (PMID 34696514, 2021). "The levels of TLR3, TLR7, myeloid differentiation primary response 88 (Myd88), and RIG-I were up-regulated due to viral infection, which were decreased, as expected, in the presence of 3D, oseltamivir, or ribavirin." (PMID 33670217, 2021). "In this study, we used hNPCs and astrocytes and detected upregulation of TLR3 levels after ZIKV infection, consistent with previous studies using poly(I·C) or bacterial or viral infection." (PMID 33658344, 2021). "However, TLR3 may only be differentially expressed in the norovirus-infected HIEs dataset due to the timing of sample collection (48 h post-infection) since an amplification of the baseline expression level of TLR3 during viral infection of intestinal epithelial cells is part of the ISG response." (PMID 34205050, 2021). "Given that viral infections may trigger either the development of inflammatory renal disease or the worsening of preexisting renal disease, activated signaling through Toll-like receptor 3 (TLR3) reportedly plays a crucial role in the pathogenesis of glomerulonephritis (GN)." (PMID 33820486, 2021). "As key components of intercellular signal transmission and regulation, the expression of cytokines including inflammatory factors (IL-1β and IL-8) and toll-like receptors (TLR2, TLR3, and TLR7) increased significantly after viral infection." (PMID 33897703, 2021). "TICAM-1 is a protein known to interact with the cytoplasmic tail of Toll-like receptor 3 (TLR3) and is reported to regulate antiviral activities in several virus infection models." (PMID 34769416, 2021). "Polyinosinic-polycytidylic acid (poly I:C) is a synthetic analog of viral double-stranded RNA, a toll-like receptor 3 (TLR3) ligand and mimic of viral infection." (PMID 34001091, 2021). "TLR3, TLR7, TLR8, and TLR9, which recognize double-stranded RNA (dsRNA) (TLR3), single-stranded RNA (ssRNA) (TLR7/8), and CpG DNA (TLR9), are mainly involved in viral infections." (PMID 33123162, 2020). "Collectively, these results disclosed that EV71 infection predominantly induces type III IFN expression through the TLR3/IRF1/type III IFN regulatory axis in the immunopathogenesis and antiviral response to the viral infection in mouse intestine." (PMID 33203755, 2020). "Although TLR3 is identified as a major MyD88-independent PRR for the induction of type-1 IFN, in response to different viral infections, the role of TLR3 in bacterial infections is poorly understood." (PMID 32824595, 2020). "The results of the current study indicate that both TLR3- and MyD88-dependent signaling play an important role in shaping the development of innate immune responses and may help explain the complications of bacterial and viral infections in chronic oral inflammation." (PMID 32824595, 2020). "TLR3, a member of the TLR family, is an indispensable recognition receptor for host defense against viral infection, and it was the first reported antiviral TLR." (PMID 33202780, 2020). "Poly(I:C), a ligand of Toll like receptor 3 (TLR3), is structurally similar to double-stranded RNA and is, thus, used to simulate viral infections." (PMID 30886604, 2019). "Poly(I:C) is a ligand for the PRRs toll-like receptor 3 (TLR3) and the RIG-I-like receptors (RLRs), which are predominantly activated by viral infection." (PMID 30764493, 2019). "TLR3 forms homodimer and signals in an exclusively TRIF–dependent manner in response to viral infections (double‐stranded RNA [dsRNA]) and stimulates the production of IFNs." (PMID 30450666, 2019).
viral infection (continued). "Upon viral infection, Toll-like receptor 3 (TLR3) and RIG-I recruit their adaptor protein (TIR-domain-containing adapter-inducing interferon-β, TRIF for TLR3 and mitochondrial antiviral signaling protein, MAVS for RIG-I)." (PMID 30682859, 2019). "In our previous study, we confirmed that TLR3 was expressed in NCI-H292 cells, and poly (I:C), which is a synthetic viral dsRNA analogue and a TLR3 ligand to mimic viral infection, activated TLR3." (PMID 29587772, 2018). "For FEV1, statistically significant interactions between viral infection and inflammation were seen for CXCL10 and TLR3 mRNA, IL-4 and CCL24 levels." (PMID 30463560, 2018). "For FVC, statistically significant interactions between viral infection and inflammation were seen for CXCL10 mRNA, TLR3 mRNA, IL-4, IL-13, CCL5, CCL20 and CCL24." (PMID 30463560, 2018). "Among PRRs, toll-like receptor 3 (TLR3) in conjunction with TLR7 and TLR9 constitutes an effective system to monitor viral infection and replication." (PMID 29515574, 2018). "Studies that detect viral infection using PCR-based methods have determined the incidence of virus-related AECOPD to be 56%, which also contributed to our study of the TLR3 in the AECOPD." (PMID 29264743, 2018). "We found that knockdown of TLR3 largely inhibited both RSV and RV-induced TGF-β expression, and prevented the viral infection impairment of dexamethasone-induced gene expression." (PMID 28046097, 2017). "Viral infections can activate innate immune signaling within the heart through Myd88-dependent (TLR7–9) and MyD88-independent pathways (TLR3)." (PMID 29077004, 2017). "In viral infection, both host cell membrane-localized TLRs (TLR2, TLR4, detecting viral envelope proteins) and endosomal TLRs (TLR3, TLR7, TLR8, and TLR9, nucleic acid sensors) initiate signal transduction cascades leading to IFN production." (PMID 28382038, 2017). "Following virus infection, engagement of the RLR or TLR3 pathway culminates in the phosphorylation of specific serine residues in the C-terminal part of IRF3 by TBK1 or IKKε." (PMID 29084253, 2017). "Different TLR agonists are being investigated as potential therapeutic agents for the treatment of various diseases, for example, TLR3, 7, 8 and 9 agonists for cancer, TLR4 and 9 agonists for allergies and TLR3, 7 and 9 agonists for viral infections." (PMID 27148868, 2016). "Our results showed the virus recognition receptors RIG-I, TLR3, and IFI16, which possibly be the mechanism that protects MSCs themselves against virus infection." (PMID 28105439, 2016). "The inflammatory features of dsRNA mediated by TLR3 are also thought to contribute to the exacerbation of CRS and nasal polyps during viral infection." (PMID 26668716, 2015). "RIPK1 interactions with TLR3 or DAI are mediated by RHIM and play important roles during virus infection." (PMID 26297639, 2015). "dsRNA is a molecular pattern that activates both TLR3 and RIG-I-MAVS signaling in airway epithelial cells and is chosen as a model for viral infection for two reasons." (PMID 24710104, 2014). "Viral dsRNA activate PRRs such as TLR3, RIG-I, and MDA-5, which signal host cellular responses in order to try to control viral infection." (PMID 24886142, 2014). "Much of this effect is due to activation by double stranded viral RNA of Toll-like receptor 3 (TLR3) on both neurons and immune system cells as part of the defence mechanism against viral infections." (PMID 23022459, 2013). "DHA pretreatment also significantly reduced IL-6 and TNF-α pro-inflammatory cytokine production during both TLR-3 and TLR-7 microglia activation, proving that DHA can exert its anti-inflammatory properties in both types of simulated viral infections." (PMID 23398903, 2013). "Previous studies have suggested that viral nucleic acids can be recognized by TLR3, and TLR7-9 in cells after viral infection, which would then lead to the production of type I interferon and inflammatory cytokines via the IRF-3 and Nf-κB pathways." (PMID 24039959, 2013).
viral infection (continued). "Endosomal TLR3, TLR7, TLR8, TLR9 are specialized in the sensing of nucleic acids produced notably during viral infections." (PMID 24302927, 2013). "We found that mRNAs of ICAM-1, VCAM-1, E-selectin, fractalkine (CX3CL1), IL-8, TLR3, and Bcl2-A1 were activated by H1N1 viral infection and suppressed by TSL-1 treatment." (PMID 24073006, 2013). "RNAi-mediated knockdown of MSR1 expression blocks TLR3 sensing of HCV in infected hepatocyte cultures, leading to increased cellular permissiveness to virus infection." (PMID 23717201, 2013). "Discussion of the present data is somewhat hampered by lack of previous BSMC data on RLRs and the fact that relative roles of TLR3, MDA5 or RIG-I in viral infections are cell-type and virus specific." (PMID 23658644, 2013). "We found that Amantadine inhibited the TLR3 and Bcl2-A1 expressions in the presence of H1N1 viral infection compared to the TSL-1." (PMID 24073006, 2013). "TLR3 is known to bind viral dsRNA to induce secretion of type I IFN and lead to control of viral infections." (PMID 22432012, 2012). "Many recent studies utilized poly IC to activate TLR3 and/or MDA5-mediated signals in conjunction with viral infections and/or autoimmunity." (PMID 22189096, 2011). "Although this study indicates that the TLR3-mediated inflammatory response is beneficial in EMCV infections; TLR3 signaling appears to be detrimental in a number of other viral infections." (PMID 21994762, 2011). "We found that TLR3 and TLR7 play an important role in controlling viral infection through the IFN production, while RIG-I play a role in IFN induction as well as in the induction of hepatocyte apoptosis." (PMID 21695051, 2011). "TLR-1, TLR-2, TLR-3, TLR-7, TLR-8, TLR-9, and TLR-10 induce type 1 IFN production during viral infections." (PMID 22114589, 2011). "IFN-β is an important cytokine for protection against viral infections, thus we selected strains able to improve the production of IFN-β in PIE cells stimulated with the TLR3 agonist." (PMID 22046952, 2011). "Conversely, transfecting TLR3 or TLR7 into Huh7.5 cells, followed by viral infection, rendered the cells capable of IFN induction." (PMID 21695051, 2011). "The induction of TLR3 (recognizing dsRNA) and TLR7 (recognizing ssRNA) suggests enhanced vigilance against viral infection activated by type I IFNs (MYD88 was also up-regulated)." (PMID 20339534, 2010). "The relative roles of the endosomal TLR3/7/8 versus the intracellular RNA helicases RIG-I and MDA5 in viral infection is much debated." (PMID 21079690, 2010). "However, a greater understanding of the specific cellular source of TLR3 signals and TLR3 pathway changes in different stages of viral infection may assist in the design of appropriate therapeutic interventions that target this TLR3 pathway in patients with chronic viral hepatitis infection." (PMID 20936107, 2010). "Viral infections, by RSV or influenza A, have been shown to upregulate TLR-3 and TLR-4 expression in host airway epithelial cells, leading to increased signalling activity and proinflammatory cytokine production." (PMID 19505311, 2009). "Furthermore, poly (I:C) administration activates the TLR3/tank-binding kinase 1/interferon-β signaling cascade and induces proinflammatory responses in RAW264.7 macrophages, thereby mimicking a viral infection." (PMID 41254402, 2025). "CSFV infection triggers the secretion of cytokines and the synthesis of antibodies; this viral infection activates downstream signaling molecules, including MAVS, IRF3, and NF-κB, through the engagement of receptors such as RIG-I, MDA5, and TLR3 (with a primary focus on RIG-I)." (PMID 40001503, 2025). "Beyond cancer and viral infections, TLR3-based therapies have not progressed to clinical trials for other diseases, such as autoimmune disorders or allergies." (PMID 39988665, 2025).